NLRP3 (NLR family pyrin domain containing 3)
Diseases named in the same sentence as NLRP3 in open-access papers (continued):
Sharing a sentence is not in itself a finding about the gene and the disease.
parasite infection (25 papers, 2009 to 2025). "The role of NLRP3 is not fully understood, but it is a crucial component of the innate immune response to parasitic infections and its functions as a sensor triggering the inflammatory response to the invasive parasites." (PMID 38623843, 2024). "Understanding the mechanism of NLRP3 interaction with these products will help to develop advanced therapeutic approaches to treat parasitic diseases." (PMID 38623843, 2024). "This review summarizes current knowledge of the NLRP3 inflammasome’s action on the immune response to parasitic infections and aims to determine the mechanisms through which parasitic molecules either activate or inhibit its action." (PMID 38623843, 2024). "They found that during infection, NLRP3−/− and C57BL/6 WT mice showed similar parasitemia and survival rates, although the parasite burden was greater in the livers of NLRP3−/− mice than WT mice." (PMID 38623843, 2024). "NLRP3 in dendritic cells is involved in mediating Th2 and Treg cell responses to resist parasitic infections." (PMID 38756775, 2024). "ROS production has been identified as a key factor in NLRP3 inflammasome activation in parasite infections such as those by Plasmodium falciparum, Trypanosoma cruzi and Toxoplasma gondii." (PMID 36151570, 2022). "NLRP3-/-, caspase-1-/- and Asc-/- mice display more severe parasitemia and lower survival probability compared to wild-type mice." (PMID 35795683, 2022). "ROS generation has been identified as a key factor in NLRP3 inflammasome activation in parasitic infections by those such as Plasmodium falciparum, Trypanosoma cruzi, and Toxoplasma gondii." (PMID 32891167, 2020). "The role of NLRP3 in the host response to parasitic infection is just beginning to be understood but is comparatively less studied than that of bacterial or viral pathogens." (PMID 32854770, 2020). "IL-1β is a marker of NLRP3 inflammasome activation and essential for cell defense in response to parasite infection." (PMID 32891167, 2020). "It has been reported that NLRP3 activation is essential for the control of different parasitic infections." (PMID 32976511, 2020). "We demonstrated that parasite infection triggered NLRP3 inflammasome activation in the liver and increased the number of hepatic NLRP3+ and IL-1β+ macrophages in WT mice as observed in a viral hepatitis model." (PMID 29774028, 2018). "To evaluate the roles of the NLRP3 inflammasome in protection against infection, we measured parasite infection and proliferation rates in transfected FHs 74 Int cells." (PMID 29291748, 2018). "Our results demonstrate for the first time that NLRP3 is dispensable for controlling parasitemia, though it is relevant for killing of parasites in the liver." (PMID 29774028, 2018). "In order to evaluate the role of NLRP3 and caspase-1/11 in the control of the parasite infection in vivo, we analyzed the parasitemia and survival curves in the three mouse strains." (PMID 29774028, 2018). "We infected Aim2−/−, Nlrp3−/−, and Casp1−/− mice with YM-iRBCs, and found that parasitemias in Aim2−/−, Nlrp3−/−, and Casp1−/− mice were markedly lower than those in WT mice." (PMID 30470758, 2018). "It is believed that the frustrated lysosome and associated cathepsin B release and activation are one of the important mechanisms mediating NLRP3 inflammasome activation during bacterial and parasite infections." (PMID 27322427, 2016). "In our model, the NLRP3−/− and caspase-1−/− mice behaved in a manner identical to the iNOS−/− mice, with a higher magnitude of peak parasitemia compared to WT mice; however, most of the NLRP3−/−, caspase-1−/− and iNOS−/− mice survived infection." (PMID 24098823, 2013). "Of interest, both IL-1β- and NLRP3 mice presented a slight but significant lower body temperature and parasitemia in the early phase of infection." (PMID 19696895, 2009).
parasite infection (continued). "However, compared with another parasitic infection discussed here, it is noticeable that most studies regarding the NLRP3 inflammasome-E.histolytica interaction were in vitro studies." (PMID 38623843, 2024). "Another study revealed that infection of NLRP3-deficient mice with PbA sporozoites suppressed cerebral malaria pathogenesis without affecting parasitemia." (PMID 39548522, 2024). "And some autoinflammatory signaling molecules like NLRP3 may constrain type 2 responses in the context of parasitic infection, while inducing type 2 immunity in the setting of allergic inflammation." (PMID 35281022, 2022). "Interestingly, accumulating evidence indicates that NLRP3 activation is essential for the control of different parasitic infections." (PMID 32854770, 2020). "However, we found that macrophage depletion in Nlrp3−/− and Aim2−/− mice at 1 day after YM infection markedly increased parasitemia and host mortality, suggesting a critical role of macrophages during the later stage YM infection." (PMID 30470758, 2018). "Furthermore, our results clearly show that NLRP3 inflammasome is dispensable for controlling parasitemia, host survival, and the onset of adaptive immune response." (PMID 29774028, 2018). "Other groups have reported that, while Plasmodium infection stimulates NLRP3, mouse mortality caused by cerebral malaria and parasitemia were not influenced by the inflammasome." (PMID 29056735, 2016). "NLRP3 inflammasomes appear to control T. cruzi replication during the acute phase of infection, as NLRP3−/− and caspase-1−/− mice exhibit a very prominent peak parasitemia 11 d after infection." (PMID 24098823, 2013). "The defect in NO production by spleen cells isolated from the NLRP3−/− and caspase-1−/− mice could explain the high levels of parasitemia observed in the iNOS−/−, NLRP3−/− and caspase-1−/− mice." (PMID 24098823, 2013). "NLRP3 and the effector protease caspase-1 appear to participate in controlling the acute phase of T. cruzi infection, as NLRP3−/− and caspase-1−/− mice exhibit a very prominent peak parasitemia, despite their ability to secrete IL-6 and IFN-γ." (PMID 24098823, 2013). "Importantly, the Hz concentration shown to activate the NLRP3 inflammasome in vitro is similar in range to the concentration of Hz in the blood of patients with moderate parasitemia." (PMID 19696895, 2009). "However, mice deficient in NLRP3 and caspase-1 are resistant to P. yoelii YM infection and present lower levels of parasitemia than wild-type mice do, indicating that NLRP3 and caspase-1 inflammasome activation negatively modulates host immune responses to resist lethal P. yoelii YM infection." (PMID 39548522, 2024). "Recently further studies have suggested that the NLRP3 inflammasome also plays an important role in the host’s response to protozoan infection This review focuses on current advances in research on NLRP3 inflammasome activation and its inflammatory response during different parasitic infections." (PMID 38623843, 2024). "Mice lacking ASC, NLRP1, and NLRP3 are highly susceptible to parasite infection." (PMID 27378827, 2016). "Suggesting that NLRP3 is not needed for regulating parasitemia, but is still crucial for improved parasite clearance from the liver." (PMID 38623843, 2024). "In extracellular parasitic infections, on the other hand, NLRP3 inflammasome activation does not lead to pyroptosis, as this would be in favor of the parasite." (PMID 37317178, 2023). "The most studied inflammasomes regarding parasitic infections are NLRP1 and NLRP3." (PMID 37317178, 2023). "Sufficient NLRP3 inflammasome activation requires K+ efflux and NADPH oxidase induced by hemozoin in P. berghei ANKA sporozoites, suggesting NLRP3 as an essential player in cerebral malaria in mice, while not controlling parasitemia." (PMID 35795683, 2022). "A 2009 study published that the NLRP3 inflammasome contributes to cerebral malaria, but does not influence parasitemia." (PMID 29056735, 2016).
parasite infection (continued). "Thus, hsa-miR-223-3p led to a decrease in NLRP3 expression that was induced by parasite infection, but not in the basal (un-induced) NLRP3 expression." (PMID 41451223, 2025). "Whether or not the NLRP3 inflammasome contributes to malaria pathology and parasitemia has also been debated." (PMID 29056735, 2016). "However, other studies show that NLRP3, ASC, Caspase-1, IL-18, or IL-1 receptor have minor or no impact on parasitemia control or mouse survival." (PMID 30470758, 2018).
Ureteral obstruction (25 papers, 2014 to 2025). Obstruction of the flow of urine through the ureter. "We further confirmed the protective role of inflammasome-independent NLRP3 in tubular epithelial cells associated with apoptosis in vivo using a unilateral ureteral obstruction (UUO) model." (PMID 30483252, 2018). "In addition, loss of NLRP3 significantly reduced inflammation and tubulointerstitial fibrosis in mice after unilateral ureteral obstruction." (PMID 33269646, 2020). "The role of the NLRP3 inflammasome in kidney disease is further emphasized by a recent study which showed that loss of NLRP3 significantly reduced inflammation and tubulointerstitial fibrosis in mice after unilateral ureteral obstruction, a relevant model of chronic kidney disease." (PMID 28000751, 2016). "Renal inflammation has been connected to the activation of the NLRP3 inflammasome and the overproduction of IL-1β in a unilateral ureteral obstruction mouse model." (PMID 35708451, 2022). "For instance, reduced expression and maturation of IL-1β, IL-18 and caspase-1 activation and reduced tubular damage and fibrosis in an NLRP3 knockout unilateral ureteral obstruction (UUO) model was observed." (PMID 34680443, 2021). "Other reports have suggested that extracellular ATP, released from renal tissue after ureteral obstruction, activates the NLRP3 inflammasome by binding to the P2X7 receptor to induce potassium efflux and ROS production in the collecting duct epithelial cells." (PMID 30281670, 2018). "Altogether, our data demonstrate that sUA, released in the context of ureteral obstruction, is responsible for triggering inflammation and for consequent induction of fibrosis, in a Myd88- and Nlrp3- dependent manner." (PMID 28084303, 2017). "This study aimed to characterize Danggui Buxue Tang (DBT) renoprotection and relationship with NOD-like receptors family pyrin domain-containing 3 (NLRP3) inflammasome expression in rats with unilateral ureteral obstruction (UUO)." (PMID 27872860, 2016). "NLRP3 inflammasome triggers caspase-1 activation and IL-1β maturation in response to diverse stimuli in a murine model of unilateral ureteral obstruction (UUO)." (PMID 27872860, 2016). "Indeed, Clinical data from an antifibrotic drug development program also suggest that reducing NLRP3 activation attenuates fibrosis in a model of unilateral ureteral obstruction." (PMID 39238634, 2024). "NLRP3 inflammasome in renal tissues could be activated by unilateral ureteral obstruction." (PMID 27721494, 2016). "This study aimed to investigate the role of the P2X7R and NLRP3 in renal tubular epithelial-myofibroblast transdifferentiation (TEMT) and interstitial fibrosis using a rat unilateral ureteral obstruction (UUO) model." (PMID 40520155, 2025). "In a unilateral ureteral obstruction (UUO) model, caspase-1, IL-1β, and IL-18 showed increased expression, leading to NLRP3 activation, While in NLRP3 gene knock out mice, less tubular injury and fibrosis were observed after UUO." (PMID 32175320, 2020). "After undergoing unilateral ureteral obstruction (UUO), mice lacking NLRP3 demonstrated decreases in tubular apoptosis, inflammation, and fibrosis." (PMID 38740765, 2024).
dry eye (24 papers, 2015 to 2025). "NF-kB and the NLRP3 inflammasome are two key pathways that regulate expression and or activation, respectively, of dry eye–associated inflammatory mediators and have been found to be induced by dryness or high osmolarity." (PMID 37036417, 2023). "Corticosteroids inhibit both NFkB signaling and activation of the NLRP3 inflammasome, pathways involved in dry eye associated inflammation and that increase in DS activated monocytes." (PMID 34305940, 2021). "ROS activates the NLRP3 inflammasome and causes cascade reactions to promote the secretion of IL-1β and IL-18, resulting in ocular surface inflammation and forming a “vicious cycle” in dry eye." (PMID 38372846, 2024). "Understanding the expression of NLRP3 inflammasome associated with the dry eye pathology may clarify factors involved in the progression of the disease and enhance the development of targeted therapies." (PMID 25962072, 2015). "However, limited information is available on the association of NLRP3 inflammasome with dry eye." (PMID 25962072, 2015). "To investigate the involvement of the ROS/NLRP3 pathway in SiNPs-induced dry eye exacerbated by SD, we evaluated the expression patterns of NLRP3 and its adaptor protein ASC in ELGs." (PMID 40890823, 2025). "Similar trends in NLRP3 gene expression and IL-1β levels were observed in patients with dry eye syndrome." (PMID 38533385, 2024). "Although inhibiting NLRP3 activation via ROS reduction is a proposed dry eye treatment, the efficacy of this approach remains to be optimized." (PMID 38372846, 2024). "Immunofluorescence showed that EX-527 inhibited the abolition of the relative fluorescence intensity of NLRP3 by luteolin (10 mg/kg) compared with luteolin (10 mg/kg) alone in the dry eye and depressive comorbid groups (p < 0.01)." (PMID 36641776, 2023). "In a mouse model for dry eye, increases in ROS production triggered NLRP3 inflammasome formation and activation, leading to the increased secretion of bioactive IL-1β." (PMID 37371417, 2023). "We found activation and nuclear translocation of NF-kB p65 (RelA) and increased expression of NLRP3 in the corneal epithelium after 24 hours of the desiccating stress dry eye model." (PMID 37036417, 2023). "Zheng and colleagues found NLRP3, caspase-1, and IL-1b increased in impression cytology samples from patients with dry eye, as well as in cultured cells exposed to hyperosmolar medium." (PMID 36902183, 2023). "Our previous study found that AQP5-deficient mice have a stable dry eye phenotype and that AQP5 deficiency leads to pyroptosis in LGs by aggravating the ROS/NLRP3 inflammasome." (PMID 37707834, 2023). "A desiccating stress-induced dry eye mouse model with elevated levels of NLRP3 inflammasome, ASC, and CASP1 has been detected together with mature IL-1β and IL-18." (PMID 36614174, 2023). "In dry eye patient tears, the administration of calcitriol effectively alleviates the hyperosmotic stress induced by NLRP3-ASC-CASP1-GSDMD pyroptosis cascade." (PMID 36614174, 2023). "The upregulation of NLRP3 inflammasome is noticed in the tears and ocular surface of dry eye patients." (PMID 36299901, 2022). "In this investigation, an NLRP3 inhibitor was successfully encapsulated in polydopamine-based microgels and used for dry eye treatment." (PMID 35721850, 2022). "MiR-223 decreases hyperosmolarity-induced inflammation through downregulating NLRP3 activation in human corneal epithelial cells and dry eye patients." (PMID 36299901, 2022). "In addition, the observation by Dartt and colleagues of P2X7 immunoreactivity in the NLRP3 inflammasomes of rat conjunctival goblet cells points to a role for these purinoceptors in the ocular surface inflammation that is an important pathogenic factor in the progression of clinical dry eye." (PMID 34203249, 2021).
dry eye (continued). "In dry eye conditions, human patients with environment-induced dry eye, murine models of dry eye, and alkali-burned mice all showed increased mRNA levels of NLRP3 in their conjunctival epithelium." (PMID 32019187, 2020). "Zheng and colleagues showed that reactive oxygen species induced NLRP3 expression by the corneal epithelium in a dry eye mouse model." (PMID 28273882, 2017). "Since NLRP3 inflammasome has a vital function in modulating inflammation and immune responses, we detected its expression in human dry eye." (PMID 25962072, 2015). "NLRP3 mRNA expression showed higher levels in both dry eye groups compared with controls, with a comparably significant elevation in the SSDE group (relative 2.47-fold upregulation, p<0.05)." (PMID 25962072, 2015). "The NLRP3 inflammasome is activated in mice with experimentally induced dry eye." (PMID 36902183, 2023). "In addition, ROS has been reported to activate the NLRP3 inflammasome in environment-induced dry eye syndrome and conjunctivitis, and a significant increase in inflammatory factors, such as IL-1β, was observed." (PMID 33663554, 2021). "In summary, based on tear samples and conjunctival impression cytology specimens of dry eye patients, we found that the expressions of NLRP3 inflammasome and its downstream inflammatory factors-caspase-1, IL-1β and IL-18 are upregulated in dry eye patients, especially in SSDE." (PMID 25962072, 2015). "A recent study reported that reactive oxygen species could trigger NLRP3 inflammasome and lead to caspase-1 auto-activation and maturation of proinflammatory cytokines IL-1β in dry eye murine models." (PMID 25962072, 2015). "Further research should focus on the regulatory mechanism of NLRP3 inflammasome in dry eye inflammation; the function of IL-18 in dry eye; and whether inhibition of inflammasome components can serve as a viable target for therapeutic development in dry eye." (PMID 25962072, 2015). "In the current study, we found that mRNA and protein expressions of NLRP3 inflammasome were upregulated in human dry eyes, especially in SSDE; the downstream inflammatory factors caspase-1, IL-1β, and IL-18 were also elevated in dry eye patients." (PMID 25962072, 2015). "However, the alteration of NLRP3 inflammasome in the tears and ocular surface of dry eye patients has not been reported until now." (PMID 25962072, 2015). "Moreover, increased NLRP3 protein levels have been detected from the ocular surface epithelium of patients with non-Sjögren syndrome dry eye, which could be evidence of the local accumulation of cellular NLRP3 protein in corneal diseases." (PMID 32271889, 2020).